C5orf58 (chromosome 5 open reading frame 58)
Tractability: No criterion of Open Targets' tractability assessment is met for any kind of drug.
Gene: Protein-coding gene on chromosome 5 (170,229,104 to 170,252,575, forward strand). Ensembl gene ENSG00000234511.
Subcellular location (Human Protein Atlas): Centriolar satellite; Cytokinetic bridge; Cytosol
Genetic constraint (gnomAD): Loss-of-function variants: 1 observed, 1.8 expected, observed/expected ratio (o/e) 0.55, 90% interval 0.18 to 1.78. That is too few expected variants to judge how well the gene tolerates losing a copy. Missense variants: 52 observed, 54.36 expected, observed/expected ratio (o/e) 0.96, 90% interval 0.76 to 1.21. Synonymous variants: 22 observed, 21.04 expected, observed/expected ratio (o/e) 1.05, 90% interval 0.75 to 1.49.
Homologues: Orthologues: chimpanzee C5H5orf58 (99% identical), macaque C5orf58 (91% identical), dog C5orf58 (73% identical), rabbit C5orf58 (69% identical), pig C5orf58 (68% identical).
Diseases named in the same sentence as C5orf58 in open-access papers:
C5orf58 is named in the same sentence as 9 diseases in open-access papers, as found by Europe PMC text mining. Sharing a sentence is not in itself a finding about the gene and the disease. The quoted sentences say what the papers report.
sarcoma (2 papers, 2021 to 2022). A usually aggressive malignant neoplasm of the soft tissue or bone. "One bioinformatic analysis reported that the overexpression of the lncRNAs ADAM6, C5orf58, CXCR2P1, FCGR2C, HCP5, HLA-H, NAPSB, NCF1B, and NCF1C reduced the sensitivity of sarcoma to ICIs." (PMID 36326232, 2022). "The expression of nine ICLs, ADAM6, C5orf58, CXCR2P1, FCGR2C, HCP5, HLA-H, NAPSB, NCF1B and NCF1C, was further investigated in different cancer types, including sarcoma." (PMID 34178688, 2021). "For C5orf58, HLA-H and NCF1C, a negative correlation of the expression of ICLs and DNA methylation was observed in sarcoma." (PMID 34178688, 2021).
coronary heart disease (1 paper, 2024). "This study focuses on four biomarkers C5orf58, ZNF180, CTAG1A, and IL13RA1 that are associated with M1 macrophage polarization and bubble cell proliferation in coronary heart disease, highlighting their key roles in the pathogenesis of the disease." (PMID 39723414, 2024). "This study reveals for the first time the correlation between C5orf58, ZNF180, M1 macrophage polarization, and increased bubble cells in coronary heart disease." (PMID 39723414, 2024). "This study focuses on the roles of C5orf58, ZNF180, CTAG1A, and IL13RA1 in the polarization of M1 macrophages and the increase of bubble cells in coronary heart disease." (PMID 39723414, 2024).
glioblastoma (1 paper, 2021). The most malignant astrocytic tumor (WHO grade IV). "In addition, glioblastoma patients with a high expression of C5orf58 exhibited a disappointing response to anti-PD-1 monotherapy and worse progression-free survival." (PMID 34178688, 2021).
hepatocellular carcinoma (1 paper, 2024). A malignant tumor that arises from hepatocytes. "C5orf58 (open reading frame 58 on chromosome 5) was found to be highly methylated and expressed at low levels in hepatocellular carcinoma." (PMID 39723414, 2024).
melanoma (1 paper, 2021). A malignant, usually aggressive tumor composed of atypical, neoplastic melanocytes. "A high expression of C5orf58 in patients with melanoma in different datasets indicated worse response to anti-PD-1/anti-CTLA-4 combined therapy, leading to worse overall survival or progression-free survival." (PMID 34178688, 2021).
cancer (1 paper, 2021). A tumor composed of atypical neoplastic, often pleomorphic cells that invade other tissues. "The results showed that high expression of C5orf58 indicated worse overall survival in the pan-cancer data." (PMID 34178688, 2021).
C5orf58 also shares sentences with these, for which no sentence is quoted: and heart disorders (1 paper); infection (1); lipodystrophy (1).